RN7SL834P (RNA, 7SL, cytoplasmic 834, pseudogene)
Gene: Miscellaneous RNA gene on chromosome 2 (230,507,101 to 230,507,386, forward strand). Ensembl gene ENSG00000243650.
Homologues: Orthologues: chimpanzee Metazoa_SRP (99% identical), macaque Metazoa_SRP (89% identical), rabbit Metazoa_SRP (64% identical). Paralogues in human: RN7SL45P (80% identical), RN7SL2 (79% identical), RN7SL1 (79% identical), RN7SL145P (78% identical), RN7SL3 (78% identical), RN7SL242P (77% identical), RN7SL381P (77% identical), RN7SL398P (77% identical), RN7SL118P (77% identical), RN7SL126P (77% identical), RN7SL473P (77% identical), RN7SL19P (76% identical), and 701 more.